SHH (sonic hedgehog signaling molecule)
Diseases named in the same sentence as SHH in open-access papers (continued):
Sharing a sentence is not in itself a finding about the gene and the disease.
bladder (1 paper, 2021). "Similarly, SHH signalings contribute to bladder development during embryogenesis, but it can also impact bladder tumorigenesis and cancer stemness in adulthood." (PMID 35004540, 2021). "In this study, we determined the temporal and spatial expression patterns of SHH signaling components in the developing human fetal bladder tissue samples by immunohistochemistry, and we explored the possible role of SHH signaling in the formation and development of human urinary bladder." (PMID 35004540, 2021).
bone sarcoma (1 paper, 2020). A sarcoma that arises from the bone. "This review discusses the current knowledge about the involvement of the SHH signaling pathway in skeletal development, pediatric bone sarcoma progression and the related therapeutic options that may be possible for these tumors." (PMID 32110934, 2020).
bone tumors (1 paper, 2020). "To better understand the role of the SHH pathway in the development of primary bone tumors, we first compared the gene expression of the main components of the SHH cascade in seven ES cell lines with those measured in seven OS cell lines, using RNAseq analysis." (PMID 33228057, 2020).
Brain atrophy (1 paper, 2007). Partial or complete wasting (loss) of brain tissue that was once present. "SHH protein diffuses into the brain following a ventromedial-to-lateral pattern, which coincides with the direction of brain atrophy progression in perlecan-deficient embryos." (PMID 17411441, 2007).
brain glioma (1 paper, 2018). A malignant glioma that involves the brain. "Furthermore, dysregulation of Gli-1 may result in aberrant activation of the SHH pathway during initiation of brain glioma." (PMID 29867331, 2018).
buphthalmos (1 paper, 2021). "In human patients, increased eye size (buphthalmos) may be caused by mutations in SHH signaling pathways." (PMID 33996806, 2021).
cataract (1 paper, 2022). Partial or complete opacity of the crystalline lens of one or both eyes that decreases visual acuity and eventually results in blindness. "The AM+A phenotype was observed in 73% (8/11) of assessed SHH variant carriers and is likely a secondary result of the cataracts distorting the focus of the lens." (PMID 35749127, 2022). "Although there do not appear to be reports of nonsyndromic cataracts caused by SHH mutations in the literature, the SHH pathway is important for lens development." (PMID 35749127, 2022).
Cerebellar atrophy (1 paper, 2016). Cerebellar atrophy is defined as a cerebellum with initially normal structures, in a posterior fossa with normal size, which displays enlarged fissures (interfolial spaces) in comparison to the foliae secondary to loss of tissue. "For example, the Sonic Hedgehog (SHH) pathway has been implicated in the etiology of structural and cognitive defects in a mouse model of DS, including cerebellar atrophy." (PMID 27472900, 2016). "Interestingly, IFN signaling has been shown to crosstalk with the SHH pathway, and cerebellar atrophy is also a hallmark of Type I Interferonopathies." (PMID 27472900, 2016).
Cerebellar dysplasia (1 paper, 2024). Cerebellar dysplasia (abnormal growth or development) is defined by abnormal cerebellar foliation, white matter arborization, and gray-white matter junction. "Loss of SHH pathway inhibition in neural stem cells and GCs from lack of GPR161 and SUFU, which promotes cleavage of GLI3 into the transcriptional repressor GLI3R, can lead to hyperproliferation and cerebellar dysplasia." (PMID 39137043, 2024).
Cerebellar medulloblastoma (1 paper, 2019). "The SHH pathway is a central regulator of cerebellar development and its dysregulation has been implicated in the generation of a substantial fraction of the cerebellar medulloblastomas (MBs), which have been classified in four different molecular subgroups, WNT, SHH, group 3 and group 49,10." (PMID 31558698, 2019).
cerebral infarction (1 paper, 2024). An ischemic condition of the brain, producing a persistent focal neurological deficit in the area of distribution of the cerebral arteries. "At the molecular level, CTLD and 4-PBA rescued ER stress and ferroptosis but promoted the SHH signaling pathway in cerebral infarction rats." (PMID 38650626, 2024). "Overall, this study revealed that CTLD may alleviate cerebral ischemia symptoms by activating the SHH pathway in cerebral infarction rats, inhibiting ER stress-induced ferroptosis, and promoting angiogenesis." (PMID 38650626, 2024).
cholesteatoma (1 paper, 2024). A pathologic process characterized by the proliferation of keratinizing squamous epithelium resulting in the accumulation of keratin and cells in the middle ear and/or mastoid. "Our previous studies showed up-regulation of the SHH gene protein in pediatric and adult cholesteatoma cases compared with control skin." (PMID 38535082, 2024). "To examine cholesteatomas from an ontogenetic point of view, we chose to evaluate the Sonic hedgehog (SHH) gene protein." (PMID 38535082, 2024). "The increased expression of the SHH gene protein in the involvement of the perimatrix indicates endodermal gene involvement in the expansion of cholesteatoma." (PMID 38535082, 2024). "However, because of the limited information available on SHH’s role in cholesteatoma, targeted studies should be carried out to gather more evidence about its role in cholesteatoma pathogenesis." (PMID 38535082, 2024). "However, there is scarce information about the role of SHH in cholesteatoma development." (PMID 38535082, 2024). "We found statistically significant differences and a tendency for statistically significant differences between the relative numbers of HβD-2, HβD-4, Ki-67, NF-κβ, SHH, VEGF, and TIMP-2-containing cells in both cholesteatoma groups, compared with the control group." (PMID 38535082, 2024). "Our study suggests that the SHH gene plays a role mainly in the development of human cholesteatoma, and it is not age dependent." (PMID 38535082, 2024). "Additionally, to our knowledge, several tissue factors such as SHH, HβD-4, and TIMP-4 have not been analyzed in cholesteatoma tissue." (PMID 38535082, 2024).
chorioamnionitis (1 paper, 2024). A morphologic finding indicating inflammation of the fetal sac membranes. "We found that chorioamnionitis led to decreased SHH signaling in Purkinje cells and accelerated maturation of GCs, with decreased SHH expression in chorioamnionitis confirmed at the protein level." (PMID 38200558, 2024). "We demonstrate that exposure to chorioamnionitis decreases the number of Purkinje cells in the cerebellum and impairs proliferation signaling from Purkinje cells to GCs in the EGL by decreased sonic hedgehog (SHH) signaling." (PMID 38200558, 2024).
colitis (1 paper, 2016). Inflammation of the colon. "Taken together, our data suggest that administration of SHH inhibitors could be an effective strategy to prevent colitis-induced colorectal carcinogenesis, mainly by targeting IL-6 signaling, ablating CSCs, and suppressing oncogenic inflammation, achieving chemoquiescence ultimately." (PMID 26716648, 2016).
congenital hypopituitarism (1 paper, 2020). "To conclude, we describe 3 patients and an aborted fetus with biallelic variants in TBC1D32 ̧ a ciliary gene implicated in SHH signaling and leading to the correct localization of Gli2, a protein that is significantly implicated in the aetiology of congenital hypopituitarism and related disorders." (PMID 32060556, 2020).
COVID-19 (1 paper, 2025). A disease caused by infection with severe acute respiratory syndrome coronavirus 2. "Furthermore, this study also identified the unique downregulation of the SHH gene at the 12-week mark in recovered critical COVID-19 patients." (PMID 41141600, 2025). "Long-term anosmia related SHH gene was upregulated in recovered critically-ill COVID-19 patients." (PMID 41141600, 2025).
craniopharyngioma (1 paper, 2022). A benign, partly cystic, epithelial tumor of the sellar region, presumably derived from Rathke pouch epithelium. "Similarly, the association between pathways in cancer and ACPs has not been reported, but the three most significant key genes (CDH1, WNT5A, and SHH) have been closely/positively associated with craniopharyngioma." (PMID 36387067, 2022).
craniosynostosis (1 paper, 2016). Craniosynostosis is defined as the premature fusion of one or more cranial sutures leading to secondary distortion of skull shape resulting in skull deformities with a variable presentation. "The phenotypes for syndromes such as these, while not identical, do have several phenotypes indicative of aberrant SHH signaling including widening of the midface, cleft lip/palate, micrognathia, craniosynostosis and oral/dental anomalies." (PMID 27799912, 2016).
cyst (1 paper, 2024). A sac-like closed membranous structure that may be empty or contain fluid or amorphous material. "In the 2022 classification, OKC remains classified as a cyst; molecular studies have detected frequent mutations in the tumor suppressor gene PTCH1, a gene that activates the SHH pathway, leading to aberrant epithelial proliferation, sparking debates on whether OKC is a cyst or a cystic neoplasm." (PMID 38750607, 2024).
dental caries (1 paper, 2023). The decay of a tooth, in which it becomes softened, discolored, and/or porous. "A total of 39 independent vQTLs with p < 1 × 10−6 were identified, some of which were located in or near genes with plausible biological roles in dental caries (IGFBP7, SLC5A8, and SHH involved in tooth development and enamel mineralization)." (PMID 36981009, 2023).
disc degeneration (1 paper, 2018). "We have previously shown that SHH signaling is essential for the normal postnatal growth and differentiation of intervertebral discs elsewhere in the spine, and that loss of SHH signaling leads to pathological disc degeneration, a very common disorder of aging." (PMID 29784673, 2018).
dysplasia (1 paper, 2022). A usually neoplastic transformation of the cell, associated with altered architectural tissue patterns. "A large number of studies showed the SHH pathway to be silent in normal mature esophageal epithelial cells, but in dysplasia and cancer, the SHH pathway is activated." (PMID 36262185, 2022).
E. coli infection (1 paper, 2018). "Employing an in vivo murine model with Gli1 deletion, we further verified the role of SHH–Gli1 signaling in mediating primitive hematopoietic precursor cell activation during the granulopoietic response to systemic E. coli infection." (PMID 29535725, 2018). "The upregulated expression of SHH by more mature lin+ hematopoietic cells may provide continuing support to activation of SHH signaling in lin-committed precursor cells during the granulopoietic response to systemic E. coli infection." (PMID 29535725, 2018).
Ectrodactyly (1 paper, 2024). A condition in which middle parts of the hands and/or feet (digits and meta-carpals and -tarsals) are missing giving a cleft appearance. "Two variants with damaging PolyPhen and SIFT predictions were found in genes of the SHH pathway: rs2592595, associated with ectrodactyly, and rs11573590, found in GLI2 and PTCH3, respectively." (PMID 38785976, 2024).
endothelial dysfunction (1 paper, 2017). In vascular diseases, endothelial dysfunction is a systemic pathological state of the endothelium (the inner lining of blood vessels) and can be broadly defined as an imbalance between vasodilating and vasoconstricting substances produced by (or acting on) the endothelium. "Activation of the SHH pathway also induces the release of endothelial NO and corrects endothelial dysfunction following ischaemia-reperfusion and hypertension." (PMID 28535764, 2017).
FG syndrome (1 paper, 2019). "The Gli3‐dependent Sonic Hedgehog (SHH) signaling pathway has been implicated in the original FG syndrome and Lujan syndrome." (PMID 30729724, 2019). "Mutations that cause FG syndrome (p.R961W) and Lujan syndrome (p.N1007S) were found to compromise the mediator‐imposed constraint on GLI3‐dependent SHH signaling and result in increased transcript levels for multiple GLI3 target genes in lymphoblasts from patients." (PMID 30729724, 2019).
fibrosis (1 paper, 2019). the formation of excess fibrous connective tissue in an organ or tissue in a reparative or reactive process. "A transgenic mice model ectopically expressing SHH in the liver revealed hepatic fibrosis, signifying the role of SHH signaling in fibrogenesis in the organ." (PMID 30700007, 2019).
fluorosis (1 paper, 2021). "The SHH signaling pathway plays an important role in the pathogenesis of liver caused by fluorosis." (PMID 33637095, 2021).
folate deficiency (1 paper, 2023). A nutritional condition produced by a deficiency of FOLIC ACID in the diet. "Together, our results provide evidence that folate deficiency affects DOT1L activity and the levels of H3K79me2, which is related to abnormal expression of SHH, SUFU genes and subsequently NTDs." (PMID 38093377, 2023).
Friedreich ataxia (1 paper, 2022). An inherited condition that affects the nervous system and causes movement problems. "Our results demonstrate that the pharmacological activation of the SHH pathway could be used as a target to modulate astrocyte reactivity and neuron–glia interactions to prevent neurodegeneration in Friedreich’s ataxia." (PMID 35413853, 2022).
fungal infection (1 paper, 2022). "Among these genes, sonic hedgehog (SHH, corresponding unigenes IDs: TCONS_00013967 and TCONS_00013968) has been implicated in immunity, acute lung injury, and fungal infection." (PMID 36221054, 2022).
gallstones (1 paper, 2025). Solid crystalline precipitates in the biliary tract, usually formed in the gallbladder, resulting in the condition of cholelithiasis. "The increased expression of SHH in the gallbladder epithelium of patients may indicate its role in promoting epithelial repair and regeneration in response to chronic inflammation and mechanical irritation caused by gallstones." (PMID 40003307, 2025). "Possibly, the presence of gallstones and ongoing chronic inflammation might shift the local cytokine production toward other inflammatory mediators—in this research, an increase in IL-12, SHH, NFkBp65, and HSP60 was detected in the gallbladder wall of patients." (PMID 40003307, 2025).
gastric disease (1 paper, 2014). "We use the mathematical model as a tool to gain insights into cytokine and SHH relationship during H. pylori infection and as a hypothesis generating tool to predict host responses that may be associated with gastric disease or clinical treatments that may provide a better outcome." (PMID 25364910, 2014).
germ cell tumor (1 paper, 2020). A benign or malignant, gonadal or extragonadal neoplasm that originates from germ cells. "The presence of higher copies of SMO and SHH, in addition to lower copy numbers of PTCH1 (which inhibits SMO activity) in germ cell tumors are another supporting fact of the involvement of HH signaling in germ cell cancer formation." (PMID 32245491, 2020).
graft versus host disease (1 paper, 2020). An immune system disorder that occurs after allogeneic hematopoietic stem cell transplant and is a reaction of donor immune cells against host tissues. "We and others have shown that GLI1 and GLI2 are upregulated in SSc skin and fibroblasts and SHH pathway activation plays an important role in the pathogenesis of tissue fibrosis both in scleroderma and sclerotic graft versus host disease (GVHD)." (PMID 33303026, 2020).
heart defects (1 paper, 2012). "Interestingly, abnormal SHH expression has been observed in fetuses with DS presenting an increased nuchal translucency, a feature frequently associated with heart defects." (PMID 22912673, 2012).
hematoma (1 paper, 2020). A hematoma is a collection of blood from a vascular structure into an extravascular space. "The inhibition of the SHH signaling pathway using SMO inhibitors treatment aggravated neurological impairments, brain edema, hematoma volume, and BBB permeability in the early stage of ICH in mice." (PMID 33343302, 2020).
Hirschsprung disease (1 paper, 2023). Hirschsprung disease (HSCR) is a congenital intestinal motility disorder that is characterized by signs of intestinal obstruction due to the presence of an aganglionic segment of variable extent in the terminal part of the colon. "Trisomy 21 and mutations in the Sonic hedgehog (SHH) signaling pathway cause overlapping and pleiotropic phenotypes including cerebellar hypoplasia, craniofacial abnormalities, congenital heart defects and Hirschsprung disease." (PMID 36995257, 2023).
Hypertension (1 paper, 2022). The presence of chronic increased pressure in the systemic arterial system. "The present study aimed to explore the effects of restoration of CUL3 gene expression on the apoptosis, oxidative stress, proliferation and migration during hypertension as well as its regulation on SHH signaling." (PMID 35715796, 2022). "Due to the length of this paper, we only discussed the effects and regulatory mechanism of CUL3 and SHH signaling in hypertension in vitro and in vivo." (PMID 35715796, 2022). "Activation of the SHH signaling can improve Ang II-induced hypertension by enhancing nitric oxide (NO) release and reducing oxidative stress in the vessel wall." (PMID 35715796, 2022). "Our findings suggested the importance of the balance between CUL3 and SHH signaling in the progression of hypertension, which provides a new understanding of the regulatory mechanism of this disease." (PMID 35715796, 2022). "Collectively, restoration of CUL3 gene expression protected against hypertension through enhancing the effects of SHH activation in inhibition of apoptosis and oxidative stress for hypertension and alleviating the dysfunction of VSMCs." (PMID 35715796, 2022). "We demonstrated that restoration of CUL3 expression could protect against hypertension through enhancing the effects of SHH activation on inhibition of apoptosis and oxidative stress for hypertension and alleviating the dysfunction of VSMCs." (PMID 35715796, 2022). "Therefore, more in-depth research on CUL3 can deepen the understanding of the SHH pathway in hypertension." (PMID 35715796, 2022). "We demonstrated that restoration of CUL3 expression could relieve hypertension through enhancing the effects of SHH activation on inhibition of apoptosis and oxidative stress as well as attenuating the proliferation and migration of VSMCs." (PMID 35715796, 2022). "In the current study, our study aimed to prove that restoration of CUL3 gene expression relieved hypertension through enhancing the effects of SHH activation in inhibition of apoptosis and oxidative stress as well as attenuating the proliferation and migration of VSMCs." (PMID 35715796, 2022). "However, the relation and balance between CUL3 and SHH signaling in hypertension draw our research interests." (PMID 35715796, 2022). "In the present study, our study showed that SHH inhibitor Cycl suppressed proliferation and migration but promoted apoptosis and ROS levels in VSMCs under 100 nM Ang II condition, suggesting a dual effect of SHH signaling on the progression of hypertension." (PMID 35715796, 2022). "Drugs that can target CUL3 and SHH might have the potential to hypertension therapy in the future." (PMID 35715796, 2022). "Therefore, increasing the expression of CUL3 while using SHH activators could not only play an anti-apoptotic and anti-oxidative role in the SHH pathway, but also reduce the level of excessive proliferation and migration of VSMCs, thereby hindering the development of hypertension." (PMID 35715796, 2022).